CD4 (CD4 molecule)
Diseases named in the same sentence as CD4 in open-access papers (continued):
Sharing a sentence is not in itself a finding about the gene and the disease.
infection (continued). "As well, the fact that reverse transcriptase inhibitor zidovudine (AZT) or integrase inhibitor raltegravir (Ral) could block MDM infection following coculture of WITO-infected CD4+ T cells further validates the authenticity of the MDM infection." (PMID 34425695, 2021). "Further analysis of longitudinal CD4 count history may also provide a continuous metric of infection severity, which may be more predictive of cognitive dysfunction." (PMID 34658754, 2021). "Similar to HIV/simian immunodeficiency virus (SIV) infection, SHIV.C.CH848 infection established viral reservoirs in CD4+ T cells and myeloid cells, accompanied by productive infection and depletion of CD4+ T cells in systemic and lymphoid tissues throughout SHIV infection." (PMID 33568508, 2021). "Estimates from back-projecting the second phase decay of integrated HIV DNA for a number of individuals where their duration of infection prior to ART were available, indicated latently infected cell numbers increased with duration of untreated infection when assessed relative to 106 CD4+ T cells." (PMID 34929000, 2021). "Moreover, the functional properties expressed by circulating memory CD4 T cells can also indicate the likelihood of establishing an infection." (PMID 34229275, 2021). "At 5 and 15 days after infection, lungs were examined for numbers of CD4+ and CD8+ T cells." (PMID 34305935, 2021). "In fact, our abridged infection-treatment scheme further revealed a diminished CD4 T cell cellular responsiveness in the livers of infected-treated animals when compared to infected or naïve animals arguing in favour of a gradual cellular hyporesponsiveness following cycles of infection-treatment." (PMID 34956183, 2021). "Patients with advanced HIV disease (CD4 count <100 cells/μL) develop an indolent infection over months before progressing to a multiorgan disseminated infection involving the lung, skin, oropharyngeal mucosa, gastrointestinal tract, lymphatic system, liver, spleen, bloodstream, and bone marrow." (PMID 32564074, 2021). "The degree of metabolism of CD8 cells after infection is much stronger than that of CD4 cells." (PMID 34603402, 2021). "CD4+ T cell-dependent entry of HIV into AMs helps explain the presence of HIV in AMs despite inefficient cell-free infection, and may contribute to AM dysfunction in people living with HIV." (PMID 33594125, 2021). "Comparison of CD4+ and CD8+ T-cell frequencies indicated that the proportion of CD8+ T-cells was greater in cynomolgus macaques prior to, and also after infection when the frequency of the CD4+ subset increased but remained secondary to the CD8+ population in peripheral blood and lung MNC." (PMID 33627662, 2021). "Based on these observations on the stimulatory properties of pEVs, we decided to investigate whether infection of activated CD4+ T cells with HIV could be enhanced by pEV pre-incubation." (PMID 34249000, 2021). "Moreover, during Mtb-infection CXCR5+CD4+ T-cells accumulated within BCFs and locally produced proinflammatory cytokines required for effective macrophage activation and optimal bacterial control." (PMID 33679802, 2021). "Indeed, the frequency of CD4+ T-cells in the blood of infected mice increased from day 30 to day 60 of infection." (PMID 34685494, 2021). "Similarly, there was a delayed increase in the percentage of Mtb-specific CD4+TNF-α+T cells in the high dose infection group with a higher percentage of this subset observed at week 3 post-infection." (PMID 34484203, 2021). "Indeed, we show that Vpu-mediated CD47 downregulation leads to an enhanced capture and phagocytosis of infected CD4+ T cells by MDMs, a process that ultimately facilitates productive infection of macrophages." (PMID 34425695, 2021). "However, the limited capacity of CCT8T−/− mice to effectively polarize their CD4+ T cells in vivo to a Th2 phenotype thwarts the clearance of H. polygyrus upon re-infection even in the presence of ILC2 cells." (PMID 34083746, 2021).
infection (continued). "Hence, in theory, knowledge on the rate of decrease in CD4 cells and its distribution would help in drawing inference about the time of infection onset." (PMID 34511561, 2021). "Furthermore, we have shown that IL-17-secreting CD4 TRM cells are expanded in the nasal tissue during primary infection with B. pertussis." (PMID 33976385, 2021). "Additionally, tamoxifen significantly increased the splenic index and the percentages of CD4+ and NK+ cells on day eight post-infection." (PMID 34204678, 2021). "Here, we report that infection by Trypanosoma brucei induced depletion of macrophages in the liver, leading to the repopulation of CXCL16-secreting intrahepatic macrophages, associated with substantial accumulation of CXCR6+CD4+ T cells in the liver." (PMID 34614031, 2021). "However, it would help the patient’s immune system to quickly resolve the commencing infection by fostering faster antibody production, enabled by the vaccine-induced CD4 T cells." (PMID 33923363, 2021). "Though macrophages are more resistant to HIV infection than CD4 T cells and generate fewer virions, they can establish infection at mucosal sites and carry the virus to other locations, such as the central nervous system (CNS), lymphatic tissues, and the gastrointestinal tract." (PMID 34960781, 2021). "Re-immunisation with pRhPD1-p27 did not result in measurable pVL based on multiple tests over time following re-immunisation but enhanced primarily p27-specifc CD8+ and CD4+ T cell responses while infection-induced Nef-specific T cell responses remained unaffected." (PMID 34125864, 2021). "Because our data showed that co-expression of the gp41-derived C46 fusion inhibitor provided protection against SIV infection in up to 85% of the ITS06 CAR T cells in vitro, it is unlikely that infection of CD4+ CAR T cells was a major contributor to their short in vivo persistence." (PMID 34485613, 2021). "Interestingly, similar results were also obtained by CD4+ T cells that were isolated from C57BL/6 donor mice that already naturally cleared the infection (day 72 p.i.)." (PMID 34868049, 2021). "Therefore, the reduced expression of CXCR3 seen on Ag-specific CD4+ T cells from pMT-10 mice overexpressing IL-10 in early stages of infection likely plays a crucial role in the delayed migration of these cells into the lung parenchyma." (PMID 34554927, 2021). "SphK2 as well as the activated, phosphorylated form of SphK2 were shown to increase in CD4+ T cells during LCMV Cl 13 infection, and deletion of SphK2 led to increased virus-specific T cell responses resulting in immunopathologic fatality of infected mice with nephrosis." (PMID 34696381, 2021). "While these data were generated in macaques, they highlight the potential role of human CD4+ TRM in preventing or clearing infection and providing long-term protective immunity and suggest modalities for eliciting antigen-specific human TRM cells by vaccination." (PMID 33668777, 2021). "However, there remains a paucity of data investigating the breadth, specificity, and heterogeneity of the CD4+ T cell response during such infections." (PMID 34106992, 2021). "First, we determined whether differential infection of and Co-IR expression in specific CD4 T-cell subsets in blood and LN during ART discriminate between immunologic suboptimal responders (ISR) and immunologic responders (IR)." (PMID 34449812, 2021). "Finally, we were also able to compare the phenotype, frequency of infection, and response to homeostatic cytokines in different CD4 T-cell subsets between IR and ISR." (PMID 34449812, 2021). "Interestingly, especially in the first month of infection, the decrease in CD4 T-cell counts was related to the proliferation of NK cells, including both TIGIT+ and TIGIT− subsets." (PMID 33717085, 2021). "Heidelberg (S. Heidelberg) infection on CD4+CD25+ T regulatory cell properties in chickens." (PMID 34843525, 2021).
infection (continued). "Consequently, control and maintenance of the CD4+ lymphocyte population is vital for the resolution of infection." (PMID 34502521, 2021). "In addition, although the viral titer of intermediate potency variant V71S was slightly decreased compared to GP61 wt and Y72F infection, NP-specific CD4 T cells exhibited a similar ratio of Th1 to Tfh effectors across all three infections." (PMID 33684030, 2021). "We compared memory CD4+ T-cell subsets at only one time point after infection and vaccination." (PMID 34960185, 2021). "Moreover, SARS-CoV-2 specific memory CD4+ T cells have also been detected in the circulation several months after recovery from the infection." (PMID 34910301, 2021). "Indeed, L-Kyn treatment induced a robust increase in pulmonary Treg (CD4+CD25+Foxp3+) cells, and this finding was associated with the large expression of mRNA for Foxp3 in the two periods of infection studied." (PMID 33936043, 2021). "Interestingly, the EBV S457A/T465V mutant more strongly induced the activation of CD4+ T cells in the blood of mice within 5 weeks of infection compared with the EBV wt‐infected group (Fig EV5D)." (PMID 34605140, 2021). "Since the largest populations of activated memory CD4+ T cells reside in the intestinal tract in uninfected hosts, the early peak viral replication that occurs in primary infection is largely attributed to this massive viral replication in this vast pool of susceptible target cells in the gut." (PMID 34960667, 2021). "To identify which host immune components are crucial for viable NMII bacteria-induced protective immunity, we examined if B cell, T cell, CD4+ T cell, or CD8+ T cell deficiency in mice will significantly affect the ability of viable NMII bacteria to confer protection against virulent NMI infection." (PMID 34795669, 2021). "By tracking the CD4+ T cells that expand rapidly during infections and respond to immunotherapy, it may be possible to pinpoint or therapeutically guide cells into helpful vs. harmful roles or niches." (PMID 34350827, 2021). "Given the close links between the gut and AT, the latter’s functions may also be indirectly impacted by the massive CD4 T cell depletion observed in the gut in the early stages of infection." (PMID 34220817, 2021). "The durability of IL-10-producing CD4+ T cells post-infection demonstrated how this cytokine may contribute to optimizing the control of parasites and prevent immunity-mediated pathology during recurrent malaria infections." (PMID 34414129, 2021). "We therefore hypothesized that IL-10 would antagonize control of M. tuberculosis infection by impairing the translocation of CD4+ T cells into the lung parenchyma, where they could interact with infected phagocytes to induce control of infection." (PMID 34554927, 2021). "It has been possible to determine that at early steps of infection, at the entry step, the tropism is almost the same, represented by CD4+ and CD8+ T cells, although, consistent with reports in humans, HTLV-1 establishes a more robust infection in both CD4+ and CD8+ T cells, compared to HTLV-2." (PMID 34360767, 2021). "Therefore, we further characterized the PD-1highFOXP3+ and PD-1lowFOXP3+ cells in HIV-infected CD4+ T cell cultures in the presence of Efavirenz added 28 h after infection." (PMID 34446704, 2021). "We further provide a sort strategy to isolate, from PBMCs, a population of highly permissive CD4+ T cells, which can serve as a model for understanding HIV susceptibility in vivo because the same subset was preferentially targeted for infection in individuals with viremia." (PMID 33910003, 2021). "In this study, we found CD4+ TM cells were down-regulated in lung tissue of patients with COPD, which may lead more susceptible to infection by bacteria or viruses." (PMID 34093570, 2021).
infection (continued). "In cases where a live virus vaccine has been used, both cell types may play a role, as in orthopoxvirus infection, where depletion of either CD8+ or CD4+ T cells affected protection from secondary infection." (PMID 33222411, 2021). "We confirmed the ability of the eGFP/mTagBFP2 expressing dual-fluorescent reporter virus to identify the presence of latently (blue, BFP+) and productively (green, GFP+ or cyan, GFP+ BFP+) infected Jurkat and primary CD4+ T-cells by fluorescence microscopy after infection with R7GEmTB." (PMID 34194479, 2021). "In the same preclinical model system of EBV infection, depletion of CD8+ T cells and NK cells or pharmacological inhibition of predominantly CD4+ T cell responses leads to higher viral loads and associated lymphomagenesis carrying primarily the latency III infection program." (PMID 34778072, 2021). "Adverse effects on the production, maturation, and/or differentiation of T or B lymphocytes may result in reduced antibody response, and decreased CD4:CD8 ratios and NK-cell function can lead to increased risk of infection due to a wide range of pathogens." (PMID 34712855, 2021). "Likewise, tissue CD4+ T cells have been demonstrated to migrate out of mucosal epithelia, thereby contributing to amplification of local infection and systemic HIV-1 dissemination." (PMID 33637808, 2021). "Also, an increase in the secretory load of IFN-γ was detected in the culture medium 48 h post infection (~1500 pg ml−1) in Mtb infected macrophages stimulated with CD4 T cell." (PMID 33767335, 2021). "Patients with severe infections had lower levels of CD4+, CD19+, and CD146+ EVs than HD." (PMID 33925492, 2021). "We found that DFV-B infection in Jurkat cells closely resembled primary CD4+ T cells." (PMID 33835029, 2021). "Cytokine-producing CD4+ T cells play a crucial role in the control of Mycobacterium tuberculosis infection; however, there is a delayed appearance of effector T cells in the lungs following aerosol infection." (PMID 34554927, 2021). "Ex vivo re-stimulation of tongue CD4+ T cells revealed a pronounced IL-17 production on day 30 and even more pronounced on day 60 post infection with strain 101, while in case of strain SC5314-infected animals, no IL-17 production above baseline was detectable at these time points." (PMID 32719409, 2021). "The true durability of protection from both infection and vaccination requires characterization of all adaptive immune responses, circulating and long-lived memory B-cell and T-cell (CD4 and CD8) responses, as antibody titers and decay reflect only one aspect of immune protection." (PMID 34748607, 2021). "Indeed, the observed correlation between pre-ART proviral turnover and CD4+ decline is consistent with the notion that rapid CD4+ T-cell turnover during untreated infection is a barrier to proviral longevity during this period." (PMID 34489909, 2021). "To determine if at least some of the CD4+ T cells accumulating in the liver were specific for the infection, we re-examined our data on antigen-experienced (CD44hi) CD4+ T cells, a population that should include those cells responding to the Salmonella antigens in the spleen and liver." (PMID 34695149, 2021). "IFN-γ is secreted primarily by CD4+ T-cells as an adaptive response to infection." (PMID 35153741, 2021). "Mechanisms driving such infections can include T cell infection by CNS resident cell types such as macrophages, ongoing infection between CNS resident CD4 T cells, or trafficking of infected T cells into the CSF from other compartments and potentially subsequent reactivation from latency." (PMID 34555123, 2021). "While it is possible that clinical characteristics such as viral load, CD4+ T cell count and length of infection may impact the phenotypes observed, the findings are still relevant for vaccine design." (PMID 34764960, 2021).
infection (continued). "These cross-reactive CD4+ T cells are largely canonical memory cells and they may be the outcome of previous infections with many of the common cold HCoVs." (PMID 33777028, 2021). "Predictably, during progressive infection, CD29hi CD4+ T cells exhibited increased HLA-DR activation levels, hinting that this cell phenotype could be targeted and depleted by the virus." (PMID 34721397, 2021). "Similarly, the frequency of circulating CD4+ T cells was reduced, suggestive of potential recruitment into the site of infection." (PMID 34304252, 2021). "Cytokine production by Liver CD4 T cells remained relatively low following infection and treatment providing an additional support to the reduced granulomatous response observed after repeated cycles of infection-treatment." (PMID 34956183, 2021). "Previous studies have revealed that T. cruzi infection promotes the activation of different CD4+ T cell profiles involved in activating and regulating immune response processes that may determine the infection outcome." (PMID 34712620, 2021). "CD4–TREM-2 KO mice displayed reduced survival ratio after MHV-A59 infection." (PMID 34878838, 2021). "To track and characterize CD32+CD4+ T cells within tissue compartments, we first performed a longitudinal measurement of CD32+CD4+ T cells in tissues before infection and during SIV infection in a natural host (AGM, N=17 animals) and a heterologous host (MAC, N=18 animals)." (PMID 34220857, 2021). "In addition, while the CD8 T-cells are dispensable for controlling the pulmonary UgCl223 infection, they likely act in conjunction with the CD4 T-cells either to prevent systemic dissemination or to control the brain infection." (PMID 35186781, 2021). "Taking advantage of a Jurkat cell line expressing human-mouse chimeric CD47, which is relatively unresponsive to Vpu modulation, we validated that Vpu-mediated CD47 downregulation contributes to phagocytosis of HIV-1-infected CD4+ T cells by MDMs and facilitates productive infection of MDMs." (PMID 34425695, 2021). "Furthermore, a recent study conducted in rhesus macaques demonstrated that repeated vaginal exposure to semen resulted in lower CCR5 expression on CD4+ T cells and reduced infection by Simian Immunodeficiency Virus." (PMID 34077596, 2021). "Importantly, permissive monocyte recruitment is mediate by IFN-γ produced by Th1 cells, as depletion of CD4+ T cells abrogated virtually all IFN-γ mRNA from the lesion site 21 days post-infection." (PMID 34557194, 2021). "CD4 T cell activation was also significantly lower in the 3D model on day 8 post-infection." (PMID 34603299, 2021). "Taken together, these results demonstrated that infection of DFV-B reporter virus in primary CD4+ T cells could directly identify live latently infected cells." (PMID 33835029, 2021). "Similar to the NK1.1+ cells in brains of TKO mice in the acute phase of infection, it seems that CD4+ T cells in the brain of TKO mice in the chronic phase of infection could compensate for the reduced CD8+ T cell response." (PMID 33968021, 2021). "Most of the latent or hibernating HIV proviruses are capable of entering into a fully productive lytic infection but await optimal conditions, that usually arise following the reactivation of quiescent memory CD4+ T-cells, which again make them metabolically active." (PMID 33918134, 2021). "Post interaction, the cytokines released from with CD4+ T cells accelerate the B cell activation leading to clonal expansion and specific antibody production to neutralize the virus and ultimately control the spread of infection." (PMID 34276652, 2021). "During the HIV life cycle, cell-free viral particles bud from productively infected cells and initiate spreading infection through gp120-mediated binding to CD4 and subsequent engagement of the CCR5/CXCR4 chemokine coreceptors resulting in gp41-dependent virion fusion." (PMID 34418431, 2021).